PTH (parathyroid hormone)
Diseases named in the same sentence as PTH in open-access papers (continued):
Sharing a sentence is not in itself a finding about the gene and the disease.
xerostomia (1 paper, 2013). Dryness of the mouth resulting from reduced salivary secretion. "Therefore, the higher salivary level of PTH and cortisol in menopausal women with xerostomia suggests that they are at higher risk of bone mineral density loss, and we have recently found that menopausal women who lose bone mineral density may experience xerostomia." (PMID 25512755, 2013).
tumor (234 papers, 1980 to 2026). "MiR-517c-3p, a member of the chromosome 19 miRNA cluster (C19MC), demonstrates significant overexpression in PCs and is associated with higher serum calcium and PTH levels, as well as increased tumor weight." (PMID 41210508, 2025). "Other less common causes include osteolysis, ectopic production of PTH by tumours, excess production of extra-renal calcitriol, and mechanisms mediated by prostaglandins." (PMID 40142228, 2025). "Preoperative serum intact PTH value is associated with tumor volume of the lesion responsible for PHPT." (PMID 38525667, 2025). "Upregulated in PCa. miR-222-3p inhibits CDKN1B/p27; miR-517c-3p associated with higher Ca, PTH, tumor weight." (PMID 41210508, 2025). "Even if larger tumours or high serum levels of PTH and calcium indicate a risk of malignancy, the preoperative diagnosis of PC remains a major challenge in clinical practice." (PMID 40525887, 2025). "HHM is induced by overproduction of PTHrP, a hormone similar to parathyroid hormone (PTH, encoded by the PTH gene), in tumor cells." (PMID 36435947, 2022). "Brown tumour is a rare tumour-like lesion of the bone, which is considered as an end-stage lesion of abnormal bone metabolism caused by persistently high parathyroid hormone (PTH) levels." (PMID 35287634, 2022). "Multivariable logistic regression models were used to analyze the association of CASR SNPs with circulating calcium, parathyroid hormone, vitamin D, and primary and secondary neoplasms." (PMID 34357109, 2021). "This analysis revealed that circulating calcium, vitamin D, and PTH levels are independently but mostly inversely associated with neoplasms at several pathological sites." (PMID 34357109, 2021). "Our analyses reveal that circulating calcium, PTH, and vitamin D levels are associated with neoplasms at multiple pathological sites, including breast, prostate, and skin cancers." (PMID 34357109, 2021). "They demonstrated that PTH was capable of increasing bone mass in myelomatous bones in vivo and that the increased bone formation was associated with reduced tumor burden." (PMID 30151009, 2018). "The most common cause of HCM is the tumor secretion of parathyroid hormone related peptide or PTH-rp (PTH-rp-oma)." (PMID 28977163, 2017). "Tumors with weak or intermediate PTH mRNA levels(+1 to +2) were significantly associated with weak tumor PTH immunoreactivity (+1 to +2)(Fisher’s exact test: P = 0.026)." (PMID 26865585, 2016). "We used the SCID-hu system and human global gene expression profiling (GEP) to shed light on molecular mechanisms associated with the effects of PTH on MM bone disease and tumor growth." (PMID 21188144, 2010). "The most common cause typically involves tumours producing parathyroid hormone-related peptide (PTHrP), which shares structural similarities with PTH (parathyroid hormone) and interacts with the same receptor (PTH receptor) in target tissues to increase serum calcium levels." (PMID 40142228, 2025). "PTH washout from needle aspiration is useful, though there is still a risk of tumor seeding." (PMID 39886673, 2024). "If the increased level of PTH is found to be associated with increased MDSCs, the patients who receive rhPTH should be thoroughly screened for cancer because MDSCs can fuel the growth of occult or microscopic tumor cells." (PMID 37085481, 2023). "Given the extent of bone loss caused by radiation, chemotherapy, and tumor-targeted therapies, there has been natural interest in the efficacy of PTH and PTHrP analogs in the oncology setting to mitigate low bone mass and prevent fractures in patients with bone metastatic disease." (PMID 37345007, 2023). "Similarly to adults, the presence of tumor-like skeleton involvement caused by massive PTH overproduction represented the hallmark of further HBS after the PT tumor removal." (PMID 37296804, 2023).
tumor (continued). "Although tumour weight is strongly associated with calcium and PTH concentration in blood, abnormal feedback and/or disturbed sensitivity to blood calcium levels could be expected in the neoplastic cells, and the dysfunction might be more marked in carcinoma." (PMID 35805976, 2022). "Furtherly, circulation tumor-derived PTHrP, which resembles PTH, was linked to cancer cachexia." (PMID 36060945, 2022). "Rarely, hypercalcemia may result from direct tumor secretion of vitamin D, which has been described in association with certain lymphomas or from ectopic tumor secretion of PTH." (PMID 34501317, 2021). "PTH and tumor-derived PTHrP enhance bone loss by uncoupling bone resorption and formation." (PMID 34182958, 2021). "After surgery, PTH levels returned to normal, indicating that increased PTH levels may be caused by tumor cells." (PMID 32791659, 2020). "Importantly we did establish that osteoblastic gene expression was upregulated in the front legs following PTH treatment, supporting that increased tumour growth in this area is linked to osteoblast number/activity." (PMID 30261597, 2018). "Tumor weight was strongly associated with circulatory concentrations of calciumand PTH." (PMID 26865585, 2016). "In addition,tumor Vitamin D receptor (VDR) mRNA levels, as measured by qRT-PCR, were notsignificantly associated with tumor PTH immunoreactivity or PTH mRNAintensity." (PMID 26865585, 2016). "BCND may be an alternative for patients with tumor sizes larger than 1 cm, but it would significantly increase the rate of transient vocal cord palsy, parathyroid auto transplantation and decreased PTH, but the risk of permanent complications was similar to the ICND group." (PMID 34983475, 2022). "BCND may be an alternative for patients with tumor sizes larger than 1 cm, but it would significantly increase the rate of transient vocal cord palsy, parathyroid auto transplantation and decreased PTH, but the risk of permanent complications was like ICND group." (PMID 34983475, 2022). "The increased drop in PTH levels 24 hours postoperatively is another indication of the tumour’s activity." (PMID 40821457, 2025). "The main goals of surgical management in PC are to evaluate tumor invasiveness, prevent further metastatic dissemination, and alleviate the systemic effects of excessive PTH secretion." (PMID 41465801, 2025). "Our findings confirm that extreme elevations in PTH and serum calcium, along with distinct ultrasonographic features (tumor size ≥ 3 cm, irregular margins, and increased depth-to-width ratio), are strong indicators of malignancy." (PMID 40507262, 2025). "HBS is common, especially after total resection of the tumor; thus, serum calcium and PTH levels should be monitored closely." (PMID 40177730, 2025). "Intraoperative parathyroid hormone (ioPTH) monitoring has been reported to be a valuable technique for confirming complete tumor resection." (PMID 40062044, 2025). "Repeated testing revealed low but detectable PTH mRNA levels in tumor tissue, with a cycle threshold (Ct) value of expression that was seen in tumor material in the real-time PCR assay with a Ct value of 28.4." (PMID 40762649, 2025). "Data for intact PTH value and tumor volume were logarithmically transformed (ln-PTH = log-transformed intact PTH value; ln-volume = log-transformed tumor volume)." (PMID 38525667, 2025). "Compared to patients with initial tumours, patients with recurrent tumours showed lower serum PTH level, lower serum calcium level, and smaller tumour diameter." (PMID 40525887, 2025). "Abnormal findings included blood tests, liver and kidney function, glycosylated hemoglobin levels, tumor markers, adrenocorticotropic hormone, cortisol, thyroid function, parathyroid hormone, growth hormone, and sex hormones levels were within normal limits." (PMID 39935661, 2025). "The use of intra-operatory PTH assays helps the rate of complete gland/tumor removal and avoids unnecessary redo surgery." (PMID 40277809, 2025).
tumor (continued). "Although her calcium levels remained stable and no definitive residual lesions were detected on imaging studies, the persistently elevated PTH levels and the cancer-type classification of her tumor certainly warrant long-term follow-up." (PMID 40434298, 2025). "PTH has been reported to promote tumor growth and potentially initiate a DNA-altering step in the cancer development process, although, this has not been definitively established." (PMID 39295728, 2024). "Patients harboring C2B PAds had lower ionized and total serum calcium levels, lower PTH levels, and smaller tumor sizes than patients harboring C2A PAds." (PMID 39409111, 2024). "The clinical management of a Brown tumour aims primarily to reduce the elevated parathyroid hormone levels by pharmacological management." (PMID 38515220, 2024). "Following surgical removal of this mass, the patient's PTH levels fell precipitously, giving credence to the potential paraneoplastic nature of this tumor." (PMID 39611185, 2024). "Immunohistochemically, the tumour was positive for parathyroid hormone (PTH), chromogranin A, PAX8, and GATA3." (PMID 39459453, 2024). "Of note, patients harboring C2B PAds had ionized calcium, total serum calcium, and PTH levels significantly lower than those of patients harboring C2A PAds, also showing a trend towards smaller tumor sizes." (PMID 39409111, 2024). "RNA was isolated from tumors and long bones of tumor-bearing mice (Cont-4T1 or Pth1rKD-4T1) treated with either vehicle or PTH for 4 weeks." (PMID 36692956, 2023). "The presence of Pth1r, however, was critical in both the tumor and the bone for the inhibitory actions of PTH on skeletal metastasis." (PMID 36692956, 2023). "Studies targeting cancer and bone metastasis have reported that altering the bone microenvironment with intermittent PTH decreases tumor engraftment in multiple myeloma and myelogenous leukemia but not in acute myeloid leukemia." (PMID 36692956, 2023). "Overall, these results suggest a conflicting role for the presence or absence of the PTH1R in cancer and metastasis, but its presence is critically important for the biological actions PTH in changing the tumor microenvironment." (PMID 36692956, 2023). "A sudden drop in PTH following the removal of the first tumour was the clue for performing an extemporaneous exam for the second mass that turned out to be non-malignant ectopic thyroid tissue." (PMID 38276049, 2023). "Gene changes with PTH treatment in the tumor–bone microenvironment is abolished with PTH1R knockdown in 4T1 cells." (PMID 36692956, 2023). "Treatment with intermittent PTH (80 μg/d/kg BW administered Monday through Friday) or vehicle (PBS) was started 24 hours after tumor injection and continued for 4 weeks." (PMID 36692956, 2023). "The mechanisms for HHCM include osteolysis at sites of bone metastases in 20% of cases, tumor secretion of PTHrP, and, less commonly, an extrarenal site of calcitriol or ectopic PTH production (< 1% each)." (PMID 37041610, 2023). "Malignant hypercalcemia is a common finding in patients with advanced cancer, involving mechanisms like tumor secretion of parathyroid hormone (PTH)-related protein, osteolytic metastases, and tumor production of calcitriol." (PMID 36909108, 2023). "In experimental models, increasing bone resorption through parathyroid hormone (PTH) stimulation or calcium restriction aggravated tumour development in bone." (PMID 36307871, 2022). "After the excision of the tumor her symptoms and laboratory results gradually improved except increasing PTH serum levels." (PMID 35090436, 2022). "Although no overwhelming evidence indicates that RFA prolongs survival, it destroys tumor cells and effectively controls serum calcium and PTH levels, thereby improving symptoms; therefore, we consider it to be a useful treatment for liver metastases." (PMID 36303876, 2022).
tumor (continued). "A positive result for chromogranin A should be combined with the data on PTH expression in the removed tissues/nodule because other chromogranin A positive tumours enter the differential diagnosis." (PMID 35805976, 2022). "In murine models, PTH improves bone mineral density by increasing osteoblast differentiation and reducing tumor cells migration." (PMID 35740530, 2022). "After confirming that the 15-min PTH level after removal of the tumor was less than 50% of the baseline value, the operation was completed." (PMID 35987641, 2022). "The levels of ALB, crCa, tumor size, tumor volume, and postoperative PTH demonstrated statistically significant differences between stages." (PMID 35663321, 2022). "The serum calcium and PTH levels of these three patients were all significantly decreased once the tumor had been removed, even intraoperatively or the day after surgery, and systemic symptoms were also significantly improved." (PMID 36303876, 2022). "Serum levels of PTH, albumin-corrected Ca, tumor size, eGFR, BMDs (all P<0.001), and clinical symptoms became milder in recent 10 years." (PMID 35784571, 2022). "ORs (95%CIs) for upper 3rd serum PTH, albumin-corrected calcium levels and tumor size in PHPT patients with famine exposure at different stages of life." (PMID 35784571, 2022). "After confirming that the 15-min intact PTH value after removal of the tumor was less than 50% of the baseline value, the operation was completed without additional resection." (PMID 35987641, 2022). "During malignancy, calcium homeostasis is progressively disrupted by the secretion of osteolytic factors such as parathyroid hormone-related protein (PTHrP) by tumor cells, which like PTH promotes osteolysis." (PMID 34357109, 2021). "There are also some experimental studies suggesting that PTH has a tumor-promoting effect and an apoptosis-inhibiting effect." (PMID 33957725, 2021). "Compared to general PC, SaPC has a later age of onset (60.50 ± 7.42 vs. 51.50 ± 8.29), relatively low levels of PTH (110.28 ± 59.32 vs. 1,156.07 ± 858.18), and a larger tumor size (6.00 ± 1.63 vs. 3.14 ± 0.70)." (PMID 34975762, 2021). "Immune blockade of PD-1 resulted in sustained reduction of pulmonary metastatic tumour burden, with concurrent normalization of both calcium and parathyroid hormone levels." (PMID 34220723, 2021). "Secretion of parathyroid hormone (PTH)-related protein (PTHrP) by tumor cells—known as humoral hypercalcemia of malignancy—accounts for 80% of cases and occurs most commonly with squamous cell tumors." (PMID 34501317, 2021). "To investigate if the tumor of the fibular head was responsible for the PTH elevation, we biopsied the tumor and stained for PTH." (PMID 33413267, 2021). "The tumor began to shrink after 1 month of treatment, and both the tumor size and i-PTH level remained low at 1 year after radiation therapy." (PMID 32572650, 2020). "This level of precision facilitates reliable detection to capture the decline within high PTH levels intraoperatively post tumor resection." (PMID 33139830, 2020). "Cases with multiple tumours are particularly more complicated, as a fall in the intraoperative PTH to the lower end of a normal range cannot guarantee that all tumours have been removed." (PMID 33147842, 2020). "Accelerated bone turnover by parathyroid hormone (PTH) is also known to induce expansion of the hematopoietic stem cell (HSC) niche which offers a safe haven for dormant tumor cells." (PMID 31405099, 2019). "Histologically, the tumour consisted of densely arranged chief cells immunohistochemically positive for PTH antigens." (PMID 31088386, 2019). "In agreement with our findings, these results support that PTH treatment can affect tumour cell seeding to a number of skeletal sites outside the long bones." (PMID 30261597, 2018). "PTH has a short half-life in vivo and was cleared from the circulation prior to tumour cell injection." (PMID 30261597, 2018).